CYP2C19 (cytochrome P450 family 2 subfamily C member 19)
Diseases named in the same sentence as CYP2C19 in open-access papers (continued):
Sharing a sentence is not in itself a finding about the gene and the disease.
Stroke (continued). "In this meta-analysis, we will assess the overall effect of CYP2C19 POC testing on major cardiovascular events (MACE), including myocardial infarction, stroke, stent thrombosis, or death as well as bleeding associated with clopidogrel therapy." (PMID 41357895, 2025). "In summary, our findings suggest that patients treated with clopidogrel based on POC CYP2C19 genotyping experience a lower risk of MACE, including myocardial infarction, stroke, stent thrombosis, and death, as well as reduced recurrent MI." (PMID 41357895, 2025). "PM distribution in the present study was comparable to that in previous cardiology studies (18.6–28.1%), reiterating that CYP2C19 PM are common among Japanese patients with a history of stroke." (PMID 40229530, 2025). "At present, both the Royal Dutch Pharmacists Association Pharmacogenetics Working Group and draft guidance from the National Institute for Health and Care Excellence in England recommend routine CYP2C19 genotyping in patients who have had a stroke." (PMID 39734623, 2024). "These and other more recent data have provided consistent results within the East-Asian population, while the value of CYP2C19 genotype as pharmacogenetic determinant in other populations of patients with stroke or TIA is still unclear." (PMID 38038819, 2024). "Since then, the role of patient CYP2C19 genotyping has gathered momentum in both cardiac and stroke medicine." (PMID 39734623, 2024). "This investigation sought to examine the outcomes of CYP2C19 genotype identification in stroke patients in Han Chinese, analyze the genotype distribution and provide a theoretical basis for individualized precision treatment." (PMID 38671468, 2024). "Nevertheless, a significant association was still found in the subgroup of patients with European ancestry between carriers of CYP2C19 LOF alleles and higher risk of stroke, after clopidogrel-based antiplatelet therapy." (PMID 38038819, 2024). "There are therefore now established and evolving roles for routine CYP2C19 genotyping in both cardiac and stroke medicine across the globe." (PMID 39734623, 2024). "Currently, there is inadequate evidence to advocate genetic testing as a standard of care and RCTs are required to assess CYP2C19 gene testing-based antiplatelet therapy for stroke prevention." (PMID 37875703, 2024). "CYP2C19-related drugs were used in diverse disorders, including depression, gastroesophageal reflux disorder, epilepsy, acute coronary syndrome, and stroke." (PMID 38535119, 2024). "Third, this study evaluated only the effect of different CYP2C19 genotypes on the clinical efficacy of ticagrelor-aspirin compared with clopidogrel-aspirin among patients receiving the drugs after stroke or TIA." (PMID 37279000, 2023). "Comparisons were made between stroke vs. control patients and between CYP2C19 intermediate metabolizer (IM)/poor metabolizer (PM) vs. extensive metabolizer (EM)/ultra metabolizer (UM) (PM: *2/*2; IM: *1/*2 vs." (PMID 37342754, 2023). "Emerging prospective evidence supports the use of a CYP2C19 genotype-guided antiplatelet strategy in stroke patients." (PMID 36082121, 2022). "In East Asians with AMI, the 1-year MACCE rates, as well as the incidence of stroke, were significantly higher in the CYP2C19 PM subgroup." (PMID 36072879, 2022). "The effects of CYP2C19 genetic variants on widely used antiplatelets, for example, clopidogrel in either CAD or stroke patients has been well-established including in Thai patients." (PMID 35250581, 2022). "In summary, CYP2C19 genotyping to guide antiplatelet therapy for a minor stroke or acute TIA in China is highly cost-effective, and the findings provide a basis for clinical treatment decisions." (PMID 33795788, 2021). "This study will provide the evidence of the relationship between CYP2C19 genotype and clinical efficacy and safety in stroke/TIA patients taking clopidogrel by pooling the results of individual studies." (PMID 29901608, 2018).
Stroke (continued). "First, this study was a stratified analysis to investigate the effectiveness of antiplatelet agents for the secondary prevention of stroke according to CYP2C19 genotypes on the basis of our previous randomized-controlled trial." (PMID 29707143, 2018). "Our findings provide certain evidence on the genetic effect of CYP2C19 on clopidogrel responsiveness in stroke patients from Saudi Arabia." (PMID 28064328, 2017). "Studies have shown that the poor metabolizer gene of CYP2C19 was related to the occurrence of coronary heart disease and stroke." (PMID 25030528, 2014). "Patients on ticagrelor were less likely to experience stroke independently of CYP2C19 or ABCB1 genotype." (PMID 22135769, 2011). "The incidence of stroke or transient ischemic attack within 90 days was 13 cases, including 8 cases of CYP2C19 gene deletion, 5 cases of CYP2C19 gene carriers, 6 cases of vertebrobasilar artery extracranial stenosis, and 7 cases of vertebrobasilar artery intracranial stenosis." (PMID 40248010, 2025). "Using the same example, a patient presenting to a stroke clinic requiring clopidogrel might have CYP2C19 testing performed, but this might be part of a broader pharmacogenetic panel." (PMID 40460990, 2025). "In the group 2, there were 5 cases of stroke or transient ischemic attack within 230 days, including 3 cases of CYP2C19 gene deletion, 2 cases of CYP2C19 gene carriers, 2 cases of vertebrobasilar artery extracranial stenosis, and 3 cases of vertebrobasilar artery intracranial stenosis." (PMID 40248010, 2025). "The incidence of stroke and transient ischemic attack within 90 days was 11 cases, including 7 cases of CYP2C19 gene deletion, 4 cases of CYP2C19 gene carriers, 4 cases of vertebrobasilar artery extracranial stenosis, and 7 cases of vertebrobasilar artery intracranial stenosis." (PMID 40248010, 2025). "In the group 1, there were 6 cases of stroke or transient ischemic attack within 30 days, including 3 cases of CYP2C19 gene deletion, 3 cases of CYP2C19 gene carriers, 2 cases of vertebrobasilar artery extracranial stenosis, and 4 cases of vertebrobasilar artery intracranial stenosis." (PMID 40248010, 2025). "In the group 3, 12 cases of stroke or transient ischemic attack occurred within 30 days, including 8 cases of CYP2C19 gene deletion, 4 cases of CYP2C19 gene carriers, 4 cases of vertebrobasilar artery extracranial stenosis, and 8 cases of vertebrobasilar artery intracranial stenosis." (PMID 40248010, 2025). "There were 20 cases of stroke or transient ischemic attack within 90 days, including 15 cases of CYP2C19 gene deletion, 5 cases of CYP2C19 gene carriers, 8 cases of vertebrobasilar artery extracranial stenosis, and 12 cases of vertebrobasilar artery intracranial stenosis." (PMID 40248010, 2025). "In this model, the same patient might present to their stroke clinic, but instead of needing to order a CYP2C19 test, the data are already embedded within their electronic health record, having been generated previously." (PMID 40460990, 2025). "Clopidogrel-treated carriers of CYP2C19 LOF alleles were found at increased risk of stroke compared to non-carriers (RR: 1.68, 95%CI: 1.04–2.71, P = 0.03)." (PMID 38038819, 2024). "It has been reported that minor stroke patients who are LoFA carriers show a reduced response to clopidogrel, and lower levels of clopidogrel active metabolites have been found in patients carrying CYP2C19 LoFAs." (PMID 38671468, 2024). "The findings of this meta-analysis suggest DAPT with ticagrelor and aspirin has a higher probability of being the superior treatment among patients with minor stroke when presence of CYP2C19 loss-of-function alleles has not been excluded." (PMID 38753327, 2024).
Stroke (continued). "The ABCD-GENE score, which incorporates age, BMI, chronic kidney disease, diabetes mellitus and CYP2C19 loss-of-function alleles, has been demonstrated among Chinese minor stroke/TIA patients to identify subjects at increased risk of stroke recurrence following clopidogrel-aspirin therapy." (PMID 38038819, 2024). "Unlike in cardiac and stroke medicine, few studies have investigated the implications of CYP2C19 variants on clinical outcome in patients with LEAD." (PMID 39734623, 2024). "Patients with coronary heart disease or stroke who are receiving clopidogrel and concomitant proton pump inhibitor (PPI) therapy while inheriting loss-of-function alleles (CYP2C19*2 or CYP2C19*3) had a 63% higher risk of developing major cardiovascular adverse events." (PMID 38420192, 2024). "The distribution of CYP2C19 genotypes, allele frequencies, and metabolic types in patients with stroke in Han Chinese patients were not correlated with sex, age, or infarction type." (PMID 38671468, 2024). "The results of pooled analyses from non-East Asian studies support that carriers of CYP2C19 LOF alleles have a significant increased risk of stroke following TIA or ischemic stroke when treated with clopidogrel." (PMID 38038819, 2024). "Overall, although any CYP2C19 LOF allele might affect the risk of MACEs (OR: 1.11; 95% CI: 0.76–1.64; P = 0.586) and stroke (OR: 1.71; 95% CI: 0.99–2.96; P = 0.054), whereas these associations without statistical significance." (PMID 35300607, 2022). "CYP2C19 no function allele carriers receiving clopidogrel had a significantly higher risk of stroke (RR: 1.92, 95% CI: 1.57–2.35) and major vascular events (RR: 1.51, 95% CI: 1.10–2.06) compared to non-carriers." (PMID 36082121, 2022). "A meta-analysis of 15 studies demonstrated a significant association between CYP2C19 no function alleles and clinical outcomes in 4,762 clopidogrel-treated patients with stroke or TIA." (PMID 36082121, 2022). "Therefore, CYP2C19 genetic testing to guide antiplatelet therapy for patients with a minor stroke or an acute TIA has more cost-effective advantages, and the additional cost is fully merited." (PMID 33795788, 2021). "Our objective was to determine whether elderly stroke patients aged over 75 years would benefit from CYP2C19-genotype-guided strategy for the secondary prevention of stroke." (PMID 33685396, 2021). "Carriers of CYP2C19 loss-of-function alleles (CYP2C19*2 and *3) have higher odds of new stroke than noncarriers and increased risk of thromboembolic complications following neurointerventional procedures." (PMID 32357528, 2020). "Plasma level of clopidogrel-active metabolite and antiplatelet ability of clopidogrel were lower, and risk of stroke and vascular events were higher in carriers of CYP2C19 *2 LOF allele than non-carriers, who were treated with clopidogrel." (PMID 32345264, 2020). "Both variants (CYP2C19*2 and ABCB1) were significant independent predictors of cardiovascular death, ACS, or stroke (ABCB1 3435 TT vs. CT/CC, HR 2.01, 95% CI: 1.30–3.11, p = 0.0017; CYP2C19 LOF alleles carriers vs. non-carriers, HR 1.77, IC95%: 1.11–2.80, p = 0.0155)." (PMID 30939847, 2019). "It appears that genes involved with drug metabolism such as MDR1, COX2 and CYP2C19 appear to have major influences on stroke outcome which may be explained by the inflammatory cascade in the recovery process of AIS." (PMID 31359356, 2019). "The risk of death, ACS, or stroke in patients with PCI was 3.58 times higher in patients who carry two copies CYP2C19 LOF alleles compared to subjects without this allele." (PMID 30939847, 2019). "The relationship of CYP2C19 genotype and clinical efficacy in stroke or transient ischemic attack (TIA) patients treated with clopidogrel monotherapy or clopidogrel plus aspirin remains unknown." (PMID 29901608, 2018).
Stroke (continued). "In the subgroup analysis conducted in patients with European ancestry, the pooled results showed that carriers of CYP2C19 LOF have an increased risk of stroke (RR: 2.69 (1.11–6.51, P = 0.03), but not of composite vascular events or bleeding after receiving clopidogrel-based antiplatelet therapy." (PMID 38038819, 2024). "This could have impacted the strength of the association between CYP2C19 LOF allele status and efficacy of clopidogrel therapy in preventing stroke recurrence, given that in a proportion of these patients antiplatelet therapy might not have been the best secondary prevention strategy." (PMID 38038819, 2024). "Similarly, European ancestry patients carrying CYP2C19 LOF alleles displayed a higher risk of stroke (RR: 2.69 (1.11–6.51, P = 0.03), but not of composite vascular events or bleeding." (PMID 38038819, 2024). "Therefore, in the present study, we conducted an updated systematic review and meta-analysis to clarify the association of CYP2C19 genotype with efficacy and safety of clopidogrel-based antiplatelet therapy in non-East Asian patients with stroke or TIA." (PMID 38038819, 2024). "CHANCE-2 clinical trial including individuals mainly carriers of the CYP2C19 loss-of-function alleles, ticagrelor and aspirin was superior to clopidogrel and aspirin in reducing the risk of subsequent stroke and did not increase the risk of severe or moderate bleeding." (PMID 37580668, 2023). "Therefore, the CYP2C19 genotype might be the most important pharmacogenetic factor in the Asian stroke population." (PMID 37208337, 2023). "In the secondary prevention of stroke, the commonly used antiplatelet drug clopidogrel needs to be converted into its active metabolite by hepatic cytochrome p450 (CYP) to take effect, and decreased effects of clopidogrel were observed in carriers of CYP2C19 loss-of-function allele." (PMID 36970504, 2023). "Recently, genetic testing in medicine has provided a new possibility for personalized medicine: the genetic sub-study of the CHANCE trial revealed that aspirin-clopidogrel only reduced the risk of stroke recurrence in non-carriers of the CYP2C19 loss-of-function allele." (PMID 37638175, 2023). "The loss-of-function allele for the CYP2C19 gene was approximately 30% of the US population and 60% in Chinese populations, clopidogrel plus aspirin reduced the risk of a new stroke only in the subgroup of patients who were not carriers of the CYP2C19 loss-of-function alleles." (PMID 37580668, 2023). "The results might suggest any CYP2C19 LOF allele of Asian patients might be associated with decreased risk of bleeding events, whereas the impacts on MACEs and stroke in all patients needed further large-scale prospective study to verify because of its non-significant increasing trend." (PMID 35300607, 2022). "This study suggested that the presence of environmental factors other than CYP2C19 PM genotype influence platelet reactivity, which was similar to the result in our study although the patient backgrounds were different because they included subacute phase stroke patients." (PMID 36090856, 2022). "Our pooled results might suggest the ischemic events of MACEs and stroke were not statistically significant, whereas patients carrying any CYP2C19 LOF allele might present with an excess risk." (PMID 35300607, 2022). "The purpose of this study therefore is to determine whether CYP2C19 genotype-guided strategy for selection of clopidogrel in elderly patients aged over 75 years with ischemic stroke can reduces the occurrence of end events and better prevent stroke recurrence?" (PMID 33685396, 2021). "Therefore, clinical testing of CYP2C19 genotype can be used to assess the incidence of clopidogrel resistance risks, which can inform the treatment plan of clinical anti-platelet aggregation for the secondary prevention of stroke." (PMID 33685396, 2021).
Stroke (continued). "The frequency of the major and minor alleles of CYP2C19*2 and CYP2C19*3 did not deviate significantly from the Hardy-Weinberg equilibrium neither in the stroke (χ2 = 1.380, P = 0.502; χ2 = 4.180, P = 0.124), nor in the control group (χ2 = 1.749, P = 0.417; χ2 = 0.400, P = 0.819)." (PMID 25030528, 2014). "Our study suggested that the CYP2C19 681AA genotype was an independent risk factor for recurrent stroke, since carriers of a reduced-function CYP2C19 allele had a two-fold risk with recurrent stroke than did noncarriers." (PMID 25030528, 2014). "Given the potential scale of CYP2C19 testing recommended by NICE and considering the acute nature of most stroke admissions, with a clear time pressure to commence definitive antiplatelet therapy, this represents a major unmet need." (PMID 39725012, 2025). "Thus, in the treatment of patients suffering from stroke, early CYP2C19 genotype testing and expedited reporting may be beneficial to patients, which is consistent with the opinion presented in another article and may help neurologists provide more individualized precision therapy to patients." (PMID 38671468, 2024). "Similarly, in cerebrovascular disease, the PRINCE trial showed that patients with minor stroke or TIA treated with ticagrelor plus aspirin exhibit reduced platelet reactivity compared to those receiving clopidogrel plus aspirin, especially so in carriers of the CYP2C19 LOF allele." (PMID 35001413, 2022). "Both CPIC and DPWG have produced clinical guidelines for clopidogrel-CYP2C19: CPIC focuses on ACS patients undergoing PCI, and DPWG on PCI for any indication, as well as stroke and TIA." (PMID 33198260, 2020). "Most stroke centers will not be colocated alongside these laboratories, meaning any sample for CYP2C19 testing will need to be transported to a separate health care organization for testing, introducing significant logistical complexity and time burden." (PMID 39725012, 2025). "The present updated meta-analysis provides moderate quality evidence of association between CYP2C19 LOF alleles and an increased risk of stroke in non-East Asian patients with stroke/TIA after receiving clopidogrel therapy." (PMID 38038819, 2024). "Inconclusive and limited results have been reported on the clinical utility of CYP2C19 genotyping in stroke/TIA patients of non-East Asian ancestries." (PMID 38038819, 2024). "Overall, these results suggest a similar impact of CYP2C19 LOF alleles on the efficacy and safety of clopidogrel in stroke/TIA patients of East-Asian ancestry compared to those of non-East Asian origin." (PMID 38038819, 2024). "Ever being prescribed aspirin did not significantly interact with CYP2C19 LoF carrier status in the model of incident stroke or MI (p>0.05)." (PMID 34903548, 2021). "Individuals with a CYP2C19 LOF genotype had a higher risk of cardiovascular death, ACS, or stroke than non-carriers in the clopidogrel group (RR 1.62, 95%CI: 1.27–2.06)." (PMID 30939847, 2019). "In conclusion, the present systematic review provides updated pooled risk estimates for the association of CYP2C19 LOF allele status with efficacy and safety of clopidogrel-based antiplatelet therapy in non-East Asian patients with stroke or TIA, including Europeans." (PMID 38038819, 2024). "We herein performed an updated systematic review and meta-analysis to quantitatively estimate the association of CYP2C19 loss-of function (LOF) status with efficacy and safety of clopidogrel-based antiplatelet therapy in non-East Asian patients affected by stroke or TIA." (PMID 38038819, 2024). "Finally, 8 articles published between 2014 and 2022 were included in the systematic review of the effect of CYP2C19 genotype on clinical outcomes of non-East Asian patients with stroke or TIA receiving clopidogrel therapy." (PMID 38038819, 2024). "Moreover, CYP2C19 genotype had no significant impacts on MACEs, MI, stroke, revascularization, definite stent thrombosis, and bleeding in the whole cohort." (PMID 35300607, 2022).